RNASEL (ribonuclease L)
Diseases named in the same sentence as RNASEL in open-access papers (continued):
Sharing a sentence is not in itself a finding about the gene and the disease.
prostate carcinoma (continued). "Nevertheless, the association between the RNASEL R462Q polymorphism and prostate cancer risk is controversial because of conflicting case–control studies." (PMID 29088852, 2017). "These future studies should lead to a comprehensive understanding of the association between the RNASEL Arg462Gln polymorphism and prostate cancer risk." (PMID 29088852, 2017). "Recent studies have found several accounts indicating RNASEL linkage to prostate cancer but there remains a significant amount of polymorphism data on RNASEL that awaits extensive population based and clinical studies." (PMID 26236721, 2015). "Among the large number of loci reported, the HPC1 locus, at 1q24-q25, harbors the gene RNASEL (encoding ribonuclease L or RNase L) a recently proposed candidate for the hereditary prostate cancer (HPC) gene." (PMID 26236721, 2015). "HPC1 or RNASEL: Located on chromosome 1q24-25 locus it was the first prostate cancer susceptibility gene to be identified." (PMID 24282788, 2013). "More recently, it has shown a minor effect, together with RNASEL, in prostate cancer risk in African American familial and sporadic cases." (PMID 24282788, 2013). "Casey and colleagues (2002) showed a 2-fold increase in prostate cancer susceptibility linked to inheritance of the RNASEL rs486907 AA genotype among mostly men of European descent." (PMID 24359571, 2013). "The R462Q mutation was known to have reduced RNASEL enzymatic activity and had already been previously shown to be associated with prostate cancer." (PMID 23056612, 2012). "Xenotropic murine leukemia virus (MLV)-related virus (XMRV) was initially identified in prostate cancer (PCa) tissue, particularly in the prostatic stromal fibroblasts, of patients homozygous for the RNASEL R462Q mutation." (PMID 21447170, 2011). "Overall, 13 articles (28 studies, 13 different first authors) were identified for evaluating the association of the RNASEL Arg462Gln or Asp541Glu polymorphism with risk for prostate cancer." (PMID 23554651, 2010). "We performed a meta-analysis of 28 studies to evaluate the association between Arg462Gln and Asp541Glu polymorphisms in the RNASEL gene and prostate cancer risk." (PMID 23554651, 2010). "The true role of the RNASEL Arg462Gln and Asp541Glu polymorphism and their influence on prostate cancer risk are similarly controversial." (PMID 23554651, 2010). "We then explored the association between these two potentially functional polymorphisms of RNASEL and prostate cancer risk." (PMID 23554651, 2010). "Recently, the Xenotropic Murine Leukemia Virus-related gammaretrovirus (XMRV) was identified in prostate tissue with a high prevalence observed in prostate cancer (PC) patients homozygous for the glutamine variant of the RNASEL protein (462Q/Q)." (PMID 20576103, 2010). "The significance of RNaseL gene polymorphisms for the development of prostate cancer is still under scrutiny." (PMID 19835577, 2009). "Germline mutations in RNASEL have been intensively studied in sporadic and familial prostate cancer but the results are contradictive." (PMID 18575592, 2008). "Germline mutations in RNASEL segregate with the disease in prostate cancer families with linkage to the HPC1 region at 1q25.3." (PMID 18575592, 2008). "Mutations in RNASEL segregate with the disease in prostate cancer families and specific genotypes are associated with an increased risk of prostate cancer." (PMID 18575592, 2008). "Two genes recently identified as conferring increased risk to prostate cancer in families (RNASEL and MSR2) participate in the response to infection and inflammation." (PMID 16539699, 2006). "In order to determine the frequency and spectrum of RNASEL germline mutations in our population, we sequenced 303 cases representing 136 prostate cancer families from Germany, Central Europe." (PMID 15714208, 2005).
prostate carcinoma (continued). "We screened for RNASEL germline mutations in familial prostate cancer patients, and performed a case–control study to examine the association of specific variants with prostate cancer risk in the Japanese." (PMID 12915880, 2003). "In the present study, we analysed RNASEL germline mutations in familial prostate cancer in Japan, and investigated the significance of the RNASEL gene in genetic susceptibility in a Japanese population." (PMID 12915880, 2003). "In the present study, we identified three variants within the RNASEL gene among 101 patients with familial prostate cancer." (PMID 12915880, 2003). "RNASEL was recently identified, and germline mutations were cosegregated within families with prostate cancer linked to the HPC1 region, at 1q24-25." (PMID 12915880, 2003). "Our study is a first to explore the links that could exist between the Arg46Gln and D541E variants of the RNASEL gene and prostate cancer in Burkina Faso." (PMID 35655265, 2022). "In particular, the RNASEL p.(Glu265Ter) variant was firstly described in prostate cancer patients and, since a reduction of protein activity was measured, a protein loss of function was hypothesized as pathogenetic mechanism." (PMID 36035419, 2022). "RNASEL, or ribonuclease L, encodes a component of the interferon-regulated 2–5A system that functions in the antiviral roles of interferons, suggesting the importance of immune function in prostate cancer susceptibility." (PMID 34207505, 2021). "While several studies have demonstrated a correlation of germline RNaseL mutations with prostate cancer, the presence of somatic mutations that inactivate RNaseL gene is rare in sporadic prostate cancer according to a mutational analysis of prostate cancer specimen and cell lines." (PMID 34809722, 2021). "Finally, the case (II-1) mutated in the RNASEL gene (c.793G>T; p.(Glu265*)) was diagnosed with prostate cancer at 53 years and with pancreatic cancer at 64 years." (PMID 34026625, 2021). "As a genetic marker, RNASEL has been linked to lethal prostate cancer." (PMID 33042807, 2020). "A role of the interferon-inducible system in the pathogenesis of an aggressive form of prostate cancer is further suggested by germline mutations in RNASEL, a gene involved in the interferon antiviral pathway, that were found to predispose men to familial prostate cancer." (PMID 30456312, 2018). "The relevance of the HPC1 (RNASEL) mutations in prostate cancer is poorly understood." (PMID 28257035, 2017). "However, previous reports showing association between RNASEL polymorphism and prostate cancer susceptibility are contradictory." (PMID 29088852, 2017). "Furthermore, in a stratified analysis by source of control, the RNASEL Arg462Gln variant was found to increase prostate cancer risk in hospital-based studies (under the recessive genetic model)." (PMID 29088852, 2017). "Rhesus macaque heterozygotes with LOF mutations in the RNASEL gene might serve as important animal models for prostate cancer." (PMID 26935327, 2016). "LOF mutations in RNASEL have been linked to susceptibility to prostate cancer in humans." (PMID 26935327, 2016). "In this study available data from the NCBI dbSNP database for the prostate cancer susceptibility gene RNASEL has been analyzed through several SNP analyzing tools and the predicted deleterious SNPs were evaluated for their potential deleterious effect on the protein function and stability." (PMID 26236721, 2015). "RNASEL resides in one of the prostate cancer (PRCA) susceptibility loci HPC1, discovered in 1996." (PMID 26236721, 2015). "Interestingly, RNase L gene (RNASEL) has been identified as a human prostate cancer susceptible (HPC1) locus and has been suggested to function as a tumor suppressor by causing apoptosis of mammalian cells through RNA degradation." (PMID 25254215, 2014). "A total of 231 prostate cancer patients were genotyped for 7 variants of RNASEL gene." (PMID 24046815, 2013).
prostate carcinoma (continued). "The main objective is to identify genetic variants of RNASEL that could be associated with high-risk prostate cancer to improve the clinical managing of these patients." (PMID 24046815, 2013). "The RNASEL gene was later implicated as harboring rare variant alleles that increase risk of prostate cancer and may account for this linkage signal." (PMID 22712434, 2012). "Taking into consideration the extensive evidence for a role of RNASEL in prostate cancer, we performed a meta-analysis of all eligible case-control studies in order to derive a more precise estimation of the association of the Arg462Gln and Asp541Glu polymorphisms in RNASEL and prostate cancer risk." (PMID 23554651, 2010). "The meta-analysis results showed evidence that RNASEL Arg462Gln and Asp541Glu polymorphisms are associated with prostate cancer risk and could be low-penetrance prostate cancer susceptibility biomarkers." (PMID 23554651, 2010). "In addition, it is noteworthy that RNAseL/HPC1 is one of the major susceptibility genes identified in familial prostate cancers." (PMID 17925854, 2007). "We identified only two sib pairs (1.4% of our families) cosegregating conspicuous RNASEL variants with prostate cancer: the nonsense mutation E265X, and a new amino-acid substitution (R400P) of unknown functional relevance." (PMID 15714208, 2005). "The RNASEL gene on chromosome 1q25 has been identified as a prostate cancer susceptibility gene." (PMID 12915880, 2003). "Thus, germline mutations in RNASEL might have diagnostic value, and the 2-5A pathway may present opportunities for developing therapies for the prostate cancer patients." (PMID 26236721, 2015). "Genotyping the RNASEL gene with routine diagnostic techniques could confer a more precise diagnosis of high-risk prostate cancer patients and increase the diagnostic accuracy above the current rate of 70% due to the relation between the genetic variants of RNASEL gene and the risk of this cancer." (PMID 24046815, 2013). "Inactivating polymorphisms of RNaseL are highly associated with familial prostate cancer in young males, and the hypothesis that such deficiencies in innate immunity leaves one vulnerable to a pathogenic retrovirus was the basis for the study that lead to the discovery of XMRV." (PMID 23537062, 2013). "Therefore, RNASEL mutations could contribute to prostate cancer by allowing clonal expansion of mutant cells that have escaped apoptosis and/or by allowing persistent infection by oncogenic viruses." (PMID 22312343, 2011). "The RNASEL Arg462Gln polymorphism was implicated in up to 13% of prostate cancer cases, with the resultant enzyme 3 times less active than the wildtype enzyme, and an association was found among Europeans and Africans between the RNASEL Arg462Gln polymorphism and sporadic prostate cancer risk." (PMID 23554651, 2010). "The endoribonuclease RNAseL (male F1 DEG ×0.43) plays a role as a tumor suppressor, and polymorphisms in this gene are involved in prostate cancer." (PMID 36982971, 2023). "Dovetailing with this, RNASEL ablation in prostate cancer cells promoted motility as well as tumor growth and metastasis." (PMID 37870957, 2023). "In affected men, RORA is typically inactivated, and RNASEL is a candidate for the hereditary prostate cancer gene (HPC1)." (PMID 36424644, 2022). "Not surprisingly, a correlation has been demonstrated between several SNPs of the human RNaseL and hereditary and sporadic prostate cancer." (PMID 34809722, 2021). "Several mutated alleles that inactivate RNASEL, including E265X, Met1Ile, and GLU256X, are associated with prostate cancer among families, as well as 1623A > C and M1I in African family lines." (PMID 33076397, 2020). "Among all the genes described as relevant in the developing of prostate cancer, the RNASEL gene has been highlighted as having the greatest effect." (PMID 24046815, 2013).
prostate carcinoma (continued). "Some specific SNPs in the involved genes, such as RNASEL at 1q24-25 (also known as Hereditary Prostate Cancer gene 1 (HPC1)), have been related to an increased risk of developing prostate cancer." (PMID 24046815, 2013). "Good results have been obtained with RNASEL gene but, as prostate cancer is a polygenic cancer, many other genes have to be analyzed and that will confer accurate information." (PMID 24046815, 2013). "The inflammatory etiology of prostate cancer (PC) is supported by the fact that the candidate gene for hereditary PC at the HPC1 locus is RNASEL, which is involved in antiviral and antiproliferative roles of interferons." (PMID 20576103, 2010). "The association between ribonuclease L (RNASEL) gene polymorphisms and prostate cancer risk has been widely reported, but the results of these studies remained controversial and underpowered." (PMID 23554651, 2010). "One of the first studies to investigate the hereditary factors associated with a predisposition for developing prostate cancer identified the HPC1 locus (hereditary prostate cancer locus-1), which is now known to harbor the RNaseL gene." (PMID 19835577, 2009). "The highly significant correlation between XMRV-positive prostate cancers and homozygosity for the QQ allel of the RNaseL SNP R462Q previously published prompted us to analyze the genotypes of all 589 PCa samples included in our study." (PMID 19835577, 2009). "In the present study, we report the testing of 589 DNA and RNA samples from sporadic prostate cancer patients for the RNaseL genotype and for XMRV sequences." (PMID 19835577, 2009). "The RNASEL gene at 1q25/HPC1 is one of three strong candidate genes for hereditary prostate cancer known to date." (PMID 15714208, 2005). "Recently, RNASEL has been proposed to be a candidate for HPC1, and a single African American prostate cancer family has been shown to have a mutation in the initiating methionine occurring in four of six brothers with prostate cancer." (PMID 14735201, 2004). "These associations need further large-scale and prospective studies to confirm the consequences of the RNASEL gene on familial prostate cancer." (PMID 12915880, 2003). "Genes linked to prostate cancer susceptibility, including RNASEL, MSR1 and MIC1, found in areas associated with familial prostate cancer, as well as TLR4, MIC1, PON1, BRCA2, CHEK2 and OGG, have been identified as contributors to prostate cancer development." (PMID 38971935, 2025). "The RNASEL gene located in 1q25 and identified as a susceptibility gene to hereditary prostate cancer, has never been studied in relation to prostate cancer in Burkina Faso." (PMID 35655265, 2022). "The role of RNASEL in hereditary prostate cancer 1 (HPC1) has an intriguing significance." (PMID 35565367, 2022). "RNaseL location within the hereditary prostate cancer 1 (HPC1) region at 1q25.3 indicates a role as a tumor suppressor in a direct or indirect manner during the malignant transformation of prostate cancer." (PMID 34809722, 2021). "As a result of genetic ancestry, differences in innate immune response has led to investigation of essential genes, such as OAS1 (OligoAdenylate Synthetase gene 1)/RNASEL, that may play a role in response to pathogens and prostate cancer disparity." (PMID 34820334, 2021). "As such studies involving polymorphisms of RNASEL were none to be found, the results of the current study would certainly be helpful in future prospects concerning prostate cancer in males." (PMID 26236721, 2015). "Our findings show that ablation or knockdown of RNase L enhanced the migration of both human prostate cancer cells and of MEF, raising the possibility that RNASEL mutations might contribute to metastasis." (PMID 26517238, 2015). "Indeed, the prostate cancer LNCaP cell line used herein lacks XMRV-restricting APOBECs and contains a deletion mutation of one allele of RNaseL, a gene critical in the innate immune response to retroviruses." (PMID 23537062, 2013).
prostate carcinoma (continued). "The discovery of XMRV in RNASEL mutant tumours demonstrated an association between XMRV infection and RNASEL deficiency but did not suggest any direct link of the virus to prostate cancer at this stage." (PMID 23056612, 2012). "This is the case with the lack of association between prostate cancer and the RNASEL (2′, 5′-Oligoadenylate-dependent RNase L) gene in a Swedish population." (PMID 22815971, 2012). "Furthermore, several genes implicated as hereditary prostate cancer tumor suppressor genes such as HPC/ELAC2 and RNASEL have been linked to increased risk of prostate cancer in African Americans." (PMID 21603658, 2011). "RNASEL has been reported as a candidate hereditary prostate cancer gene." (PMID 20027305, 2009). "RNASEL is located within the hereditary prostate cancer 1 (HPC1) region at 1q25.3." (PMID 18575592, 2008). "The RNASEL gene locus at 1q25 (HPC1) has been implicated in prostate cancer susceptibility as a result of the first genome wide linkage scan, which included 91 hereditary prostate cancer pedigrees from North America and Sweden." (PMID 15714208, 2005). "To date, three strong candidates are known, RNASEL at 1q25, ELAC2 at 17p11 and MSR1 at 8p22, each having been identified with germline mutations in prostate cancer families." (PMID 15714208, 2005). "Taken together, these results indicate that RNASEL could only account for a minor portion of familial prostate cancer in Germany." (PMID 15714208, 2005). "Due to the low frequency of germline mutations present in our sample, RNASEL does not have a significant impact on prostate cancer susceptibility in the German population." (PMID 15714208, 2005). "Regarding the common variants of RNASEL, we did not observe any significant association, neither with prostate cancer in general nor with early-onset disease." (PMID 15714208, 2005). "Six prostate cancer susceptibility loci (HPC1 at 1q24-25, PCAP at 1q42-43, HPCX at Xq27-28, CAPB at 1p36, HPC20 at 20q13 and HPC2 at 17p12) and two candidate susceptibility genes (HPC2/ELAC2 at 17q and RNASEL at 1q24-25) have been reported." (PMID 12915880, 2003). "Besides a genetic variant, the epigenetic alteration of RNASEL catalytic activity influenced by different inflammatory or infective agents would not be excluded in prostate cancer." (PMID 35565367, 2022). "One RNASEL gene variant has been implicated in as much as 13% of prostate cancer cases, and men who are homozygous for the Arg46sGln allele mutation can exhibit double the risk of developing prostate cancer when compared to men who carry no RNASEL mutated alleles." (PMID 33076397, 2020). "There is also evidence of association between prostate cancer risk and gene variants of COX-2, RNASEL and TLR4, identified in cases of hereditary prostate cancer, indicating that infection and the host response to infection may be involved in the development of prostate cancer." (PMID 28101126, 2017). "In conclusion, this meta-analysis showed evidence that the RNASEL Arg462Gln polymorphism may contribute to the risk for developing prostate cancer in African descendants and Hispanic Caucasians, but not for other descendants." (PMID 29088852, 2017). "Although XMRV was originally associated with the mutant variant of the RNASEL gene, further research could not confirm this association but did find it in about 10% of prostate cancers." (PMID 22312356, 2011). "For example, the RNASEL gene coding for Rnase L, an enzyme responsible for the induction of apoptosis and cell proliferation, has been identified within the HPC1 locus (hereditary prostate cancer 1)." (PMID 31731466, 2019). "Ribonuclease L (RNASEL), which is considered to be a tumor-suppressor gene, plays a significant role in the pathogenesis of prostate cancer through inflammation and infection." (PMID 29088852, 2017).